PDCD1 (programmed cell death 1)
Diseases named in the same sentence as PDCD1 in open-access papers (continued):
Sharing a sentence is not in itself a finding about the gene and the disease.
Sepsis (39 papers, 2014 to 2025). Sepsis is defined as life-threatening organ dysfunction caused by a dysregulated host response to infection. "In this review, we systematically present the mechanisms of immune dysregulation in sepsis and elucidate the expression and regulatory effects of the programmed cell death 1 signaling pathway on immune cells associated with sepsis." (PMID 37292207, 2023). "Programmed cell death 1 (PD-1) expression by macrophages has been associated with immune suppression during sepsis and cancer." (PMID 33320839, 2021). "The PDCD1 protein is involved in the programmed cell death pathway, whose inhibition benefits sepsis-associated microbial clearing in murine macrophages." (PMID 32276386, 2020). "Several mechanisms contribute to sepsis-induced immunosuppression, including apoptosis of immune cells, heightened regulatory T cell activity, upregulation of programmed cell death 1 on CD4+ T cells, and cellular exhaustion." (PMID 38690455, 2024). "Immunomodulatory molecules such as IL-7, IL-15, and anti-programmed cell death 1 have been identified as potential therapeutic targets to counteract immunosuppression in sepsis." (PMID 38690455, 2024). "We then specify current research developments and prospects for the application of the programmed cell death 1 signaling pathway in immunomodulatory therapy for sepsis." (PMID 37292207, 2023). "The programmed cell death 1 (PD-1) and its ligand PD-L1 pathway play a pivotal role in sepsis occurrence, development, and prognosis from various perspectives and levels." (PMID 38193090, 2023). "Recent studies have suggested that the programmed cell death 1 signaling pathway is involved in the formation of immunosuppression in sepsis." (PMID 37292207, 2023). "Antibodies against programmed cell death 1 (PD-1) receptor and the corresponding ligand (PD-L1) as well as Interleukin-7 are considered promising candidates for the treatment of sepsis and its immunological consequences." (PMID 34055825, 2021). "Programmed cell death-1/programmed death-ligand 1 (PD-1/PDL-1) is one of the key models in the development of sepsis-mediated immunosuppression, but its role in newborns is still poorly described." (PMID 34840718, 2021). "We aimed to develop a method for predicting the personal benefit of potential treatments for sepsis, and to apply it to therapy by meropenem, an antibiotic drug, and nivolumab, a programmed cell death-1 (PD-1) pathway inhibitor." (PMID 33732241, 2021). "Natural killer (NK) cells play a major role in immune tolerance after sepsis, and the programmed cell death 1 (PD-1) and programmed cell death ligand 1 (PD-L1) system mediates evasion of host immunity." (PMID 33076951, 2020). "Many mechanisms are responsible for sepsis‐induced immunosuppression, including apoptosis of immune cells, increased regulatory T cells and expression of programmed cell death 1 on CD4+ T cells, and cellular exhaustion." (PMID 30238076, 2018). "Low programmed cell death 1 (PD-1) can mitigate sepsis-related damage." (PMID 41158471, 2025). "Dot plot of these genes in sepsis single-cell data revealed the CD8+ T cell exhaustion subcluster (TS3 with high CD8+ T cell markers CD8a, CD8b, and exhaustion markers PDCD1 and CTLA4)." (PMID 37077915, 2023). "For example, programmed cell death 1 protein (PD-1) is a negative costimulatory molecule and involved in the host responses to sepsis." (PMID 28149700, 2017).
COVID-19 (37 papers, 2020 to 2025). A disease caused by infection with severe acute respiratory syndrome coronavirus 2. "Tissue-resident T cells in the lungs of COVID-19 patients exhibit altered chromatin accessibility at genes encoding cytokines like IFN-γ and IL-2, along with increased exhaustion markers (PDCD1, LAG3), driven by repressive histone marks." (PMID 40969755, 2025). "Upstream regulator analysis identified five key regulators after exposure to COVID-19 in our study, one phosphatase (PDCD1), 3 transcriptional regulators (E2F3, NUPR1 and LARP1) and one mitotic spindle protein (CKAP2L)." (PMID 35547542, 2022). "We observed sustained increase of programmed cell death 1 (PD-1) in COVID-19 patients compared with healthy donors in both CD4 and CD8 compartments." (PMID 33361110, 2021). "Among the co-inhibitory receptors, LAG3, CTLA4, and HAVCR2 were enriched in CD8+ T cells from COVID-19 patients that eventually succumbed to the disease, but PDCD1 and TIGIT were enriched in CD8+ T cells from COVID-19 patients that eventually recovered and discharged." (PMID 36119105, 2022). "Previous studies have suggested that higher expression of programmed cell death-1 (PD-1) on T cells in COVID-19 patients could signify the presence of exhausted T cells." (PMID 34611163, 2021). "Finally, exhaustion genes such as PDCD1/PD-1 or regulatory genes such as FOXP3 were under-expressed among COVID-19 compared to INFL or HTLY, mainly among TUBE early patients." (PMID 34135895, 2021). "This reduction, coupled with increased expression of exhaustion markers (PDCD1, CTLA4), suggests that T cells in severe COVID-19 are overactivated and subsequently exhausted, impairing their ability to control the virus." (PMID 39928675, 2025). "Gao and co-workers have reported that programmed cell death protein 1 (PDCD1) expression in T cells, B cells, myeloid dendritic cells, and macrophages were upregulated in COVID-19 patients and correlated with the severity of infection." (PMID 35547542, 2022). "Additionally, the expression of transcripts regulating cellular exhaustion (TIGIT, BTL4, PDCD1, and HAVCR2) was found to be similarly upregulated in severe COVID-19." (PMID 37029220, 2023). "TH1-like cells from patients with mild COVID-19 exhibited a TH1 polarization state, characterized by upregulation of effector marker genes (PDCD1, CCL5, CXCR2, CCR2, GZMA/B, NKG7, PRF1, IFNG, and CCL4) and genes involved in effector function such as CXCR4, CXCL2, ANXA1, SOCS2 and LTB." (PMID 36119105, 2022). "Indeed, patients with severe COVID-19 present lymphopenia and low CD4+ and CD8+ T cells counts, as well as high percentages of programmed cell death-1 (PD-1) expression on T cells." (PMID 36605446, 2022). "Another study also identified other cell exhaustion markers (LAG3, PDCD1 and HAVCR2) on NK cells from COVID-19 patients which could reflect that SARS-CoV-2 infection could induce these phenotypes in COVID-19 patients." (PMID 36369012, 2022). "Furthermore, the inhibitory membrane receptors expressed by CD8+ T cells, such as PDCD1 (PD1), CTLA4, and HAVCR2 (TIM3), were significantly upregulated in severe COVID-19 patients when compared with those in healthy people and mild COVID-19 patients." (PMID 34305939, 2021). "In addition, T cells exhaustion was observed in severe COVID-19 patients but not in the RP or MM COVID-19 patient, as supported by the distinct expression pattern of T cells exhaustion-related genes such as programmed cell death 1 (PD-1, PDCD1) and Tim-3 (HAVCR2)." (PMID 34305895, 2021).
lymphoma (37 papers, 2015 to 2025). A malignant (clonal) proliferation of B- lymphocytes or T- lymphocytes which involves the lymph nodes, bone marrow and/or extranodal sites. "Interestingly, multiple PDCD1-mutant lymphomas carried mutations in another tumor suppressor encoded by CDKN2A." (PMID 37723306, 2023). "A PB screen in T cells discovered PDCD1, which encodes PD-1, as a key suppressor of oncogenic T cell signaling that prevents development of T cell lymphoma in an autochthonous mouse model; human lymphomas contain deletions in this gene in up to 30% of cases, confirming clinical relevance." (PMID 32811551, 2020). "RNA-seq analysis showed enhanced activity of the PI3K-AKT-mTOR pathway, enforced HIF1-α activity and increased activity of glycolysis genes in Pdcd1-mutant lymphomas, compared to wild type Pdcd1." (PMID 38790264, 2024). "Conversely, pharmacological inhibition of ACLY curtails AP-1 hyperactivation and is toxic to PDCD1-mutant lymphomas." (PMID 37723306, 2023). "To perturb (PI3K)–AKT–mTOR signaling, glycolysis or ACLY activity in viable PDCD1-wild-type and PDCD1-mutant lymphoma cells, we incubated the six primary patient samples with respective small-molecule inhibitors of these pathways." (PMID 37723306, 2023). "Again, we also observed enhanced activity of glycolysis gene sets in PDCD1-mutant lymphomas compared to PDCD1-wild-type lymphomas." (PMID 37723306, 2023). "To test the dependency of fully transformed lymphomas with Pdcd1 deletion on the released mTOR–HIF1α–glycolysis cascade, we incubated ITK–SYK+PD-1− cells with small-molecule inhibitors of mTOR, HIF1α or glycolysis." (PMID 37723306, 2023). "Importantly, AP-1 hyperactivation in Pdcd1-deleted lymphoma cells was critically dependent on ACLY activity." (PMID 37723306, 2023). "To determine whether ACLY activity is required for PD-1-deficient lymphoma cell survival, we next incubated transformed ITK–SYK+PD-1− T cells from tamoxifen-injected ITK-SYKCD4-CreERT2;Pdcd1−/− mice with an ACLY inhibitor." (PMID 37723306, 2023). "On the one hand, it is unclear whether unleashed ACLY activity in PDCD1-mutant lymphomas regulates acetyl-CoA-dependent metabolic pathways apart from histone acetylation, similar to de novo generation of lipids." (PMID 37723306, 2023). "These treatments have shown great promise, and immune checkpoint inhibitors targeting the programmed cell death-1/programmed cell death-ligand 1 (PD-1/PD-L1) pathway in particular, have now been approved as first- or second-line treatments for melanoma, lymphoma, and other malignancies." (PMID 32917035, 2020). "Consistent with the development of an AITL condition, the transcriptome of the lymphoma samples obtained from Trp53ER/ER;Vav1ΔC/ΔC mice includes the upregulation of AITL‐specific genes such as Bcl6, Maf, Il21, Pdcd1, and Icos." (PMID 35895495, 2022). "Moreover, IFN-α treatment induces the expression of programmed cell death-1 (PD-1) on tumor-infiltrating T cells and PD-L1 on tumors, which can be neutralized using checkpoint blockade with anti-PD-1/PD-L1 mAbs, currently in clinical trials in both lymphoma and MM." (PMID 28725493, 2017). "Furthermore, as seen in the EL4 lymphoma model, a significant decrease in Pdcd1 gene expression was also seen in the Gsk3b cKO but not in Gsk3a cKO cells." (PMID 34142056, 2021).
head and neck squamous cell carcinoma (36 papers, 2015 to 2025). A squamous cell carcinoma that arises from any of the following anatomic sites: lip and oral cavity, nasal cavity, paranasal sinuses, pharynx, larynx, and salivary glands. "Although programmed cell death 1 inhibitors have demonstrated efficacy in head and neck squamous cell carcinoma and cutaneous squamous cell carcinoma, their application in TBSCC remains underexplored." (PMID 40336643, 2024). "Immune checkpoint inhibitors, such as programmed cell death 1 (PD-1) inhibitors, are the most promising drugs in the field and have been approved to treat various types of cancer, such as metastatic melanoma, head and neck squamous cell carcinoma, and urothelial carcinoma." (PMID 31058839, 2019). "Programmed cell death 1 (PD-1) inhibitors are first- and second-line treatments for recurrent or metastatic head and neck squamous cell carcinoma (HNSCC)." (PMID 38293699, 2023). "In recurrent or metastatic head and neck squamous cell carcinoma (R/M-HNSCC), survival outcomes are significantly better in patients who receive anti-programmed cell death-1 (PD-1) monoclonal antibody therapy than in those who receive standard therapy." (PMID 37366893, 2023). "Checkpoint inhibitor-based immunotherapy targeting the programmed cell death 1 (PD-1) pathway has acquired a leading role in the management of recurrent or metastatic (R/M) Head and Neck Squamous Cell Carcinoma (HNSCC)." (PMID 34771546, 2021). "Anti-programmed cell death-1 (anti-PD-1) monoclonal antibodies are immune checkpoint inhibitors (ICIs) recently introduced to treat recurrent or metastatic head and neck squamous cell carcinoma (R/M-HNSCC)." (PMID 37366893, 2023). "We analyzed the immune cell infiltrates of head and neck squamous cell carcinoma and colorectal cancers and identified a subset of CD4+ Th cells distinct from FOXP3+ Tregs that coexpressed programmed cell death 1 (PD-1) and ICOS." (PMID 35439168, 2022). "Pembrolizumab and nivolumab, monoclonal antibodies directed against the programmed cell death-1 (PD-1) receptor, are US Food and Drug Administration (FDA)- and European Medical Agency (EMA)-approved immunotherapies for head and neck squamous cell carcinoma (HNSCC)." (PMID 38398094, 2024).
viral infection (35 papers, 2014 to 2025). "The results suggest that loss of Pdcd1 association to repressive nuclear lamina is associated with the chronic phase of viral infection in exhausted CTLs (at 30 dpi)." (PMID 39083377, 2024). "Programmed cell death-1 (PD-1), an inhibitory regulator of T cell activity, has been implicated in regulating immune responses to viral infections and tumors." (PMID 28545019, 2017). "Previous reports show that chronic viral infection leads to demethylation of the regulatory regions of PDCD1, which encodes the PD-1 receptor, in mouse and human CD8+ T cells." (PMID 27302925, 2016). "Besides targeting the PDCD1 gene, these miRNAs may also be associated with cell transformation induced by viruses and may share sequences associated with virus infection complications." (PMID 34290992, 2021). "Collectively, the results validate a significant regulatory role of Blimp-1 on Pdcd1 gene expression in acute and chronic viral infection settings." (PMID 39083377, 2024). "Cd274 encodes PD-L1 and its delicate balance with programmed cell death 1 (PD-1; encoded by Pdcd1) is important for restricting CD8+ T cell-induced immunopathology during both early and late virus infections." (PMID 38536871, 2024). "Another promising option is the oncolytic virus infection which enhances the expression of programmed cell death 1 (PD1) ligand 1 (PDL1) or increases the recruitment and activation of local T cells." (PMID 36983330, 2023). "Intracellular production of IL-2, IFN-g, and TNF, and often severely reduced in persistent viral infections, and T cells also express large numbers of inhibitory receptors, including PD-1 (programmed cell death-1) and Lymphocyte-Activation Gene 3 (Lag-3)." (PMID 36678799, 2023). "In CD8+ T cells, Blimp1 and LSD1 interaction is required to repress the expression of PD1 (Pdcd1) during the acute phase of viral infection." (PMID 35154079, 2021). "Altogether, these studies indicate a differential role of the PDCD1 -606G>A polymorphic site according to the major subjacent cancer or viral disorder." (PMID 34290992, 2021). "To evaluate the role of Pdcd1 in regulating anti-viral CD8+ T cell responses, we performed a 1:1 competitive assay with control sgRNA or Pdcd1 sgRNA-containing P14 CD8+ T cells during LCMV Clone 13 viral infection." (PMID 30971695, 2019). "In chronic viral infections, results indicate that the PDCD1 demethylation levels persist in activated T cells, leading to long-term expression of PD-1 and T cell dysfunction." (PMID 31379886, 2019). "Among the overrepresented T-cell-receptor signaling genes, PD-1 (encoded by PDCD1) and CTLA-4 are important inhibitory receptors that are involved in T-cell exhaustion, which is commonly associated with persistent viral infections." (PMID 27643611, 2016). "The demethylation of the Pdcd1 promoter seen in PIT-tolerized Teff is reminiscent of the changes reported to occur in CD8+ T cells exhausted in response to chronic viral infection." (PMID 25546306, 2014). "Programmed cell death 1 (known as PD-1) and other immune checkpoint receptors may also inhibit NK cell activation, particularly in the context of viral infections or cancers." (PMID 39415291, 2024). "However, a couple of years later, it was demonstrated that PD-1 can be repressed by Blimp-1 in CD8+ T cells by suppressing the expression of NFATc1, which acts as a transcriptional activator of Pdcd1 during acute viral infections." (PMID 39062968, 2024). "The PDCD1 -606AA genotype was also associated with chronic hepatitis B virus (HBV) infection in the Chinese population, a viral infection that may progress to hepatocarcinoma." (PMID 34290992, 2021). "Programmed cell death 1 (PDCD1, best known as PD-1) and other immune checkpoints receptors may inhibit NK cell activation, particularly in viral infection and cancer." (PMID 32272610, 2020).
viral infection (continued). "Several research papers suggest that expression of co-inhibitory molecules such as PDCD1 (PD-1), HAVCR2 (Tim-3), CTLA4, and LAG3 correlates with the activated and more differentiated state of CD8+ T cells in viral infection." (PMID 37409113, 2023). "In the context of viral infection, binding of the transcription factor IFN regulatory factor 9 (IRF9) to the Pdcd1 promoter induces Pdcd1 transcription, which is also observed for the transcription factor forkhead box protein O 1 (FoxO1)." (PMID 31636634, 2019). "We focus on blockade of programmed cell death 1 (PD‐1) to induce durable immune‐mediated control of HIV, given that anti‐PD‐1 can restore function to exhausted HIV‐specific T cells and also reverse HIV latency, a long‐lived form of viral infection." (PMID 39248154, 2024). "During chronic infection with lymphocytic choriomeningitis virus (LCMV), PDCD1 mRNA levels were upregulated in “exhausted” CD8+ T cells with impaired cytokine production and proliferation, but PDCD1 was not upregulated in functional LCMV-specific memory CD8+ T cells during acute viral infection." (PMID 29255458, 2017).